ALOX12 (arachidonate 12-lipoxygenase, 12S type)
Diseases named in the same sentence as ALOX12 in open-access papers (continued):
Sharing a sentence is not in itself a finding about the gene and the disease.
prostate carcinoma (5 papers, 2010 to 2026). A carcinoma that arises from epithelial cells of the prostate gland. "ALOX12 has also been implicated in promoting tumor progression and metastasis in prostate cancer, suggesting its involvement in cell proliferation and dysregulation during carcinogenesis." (PMID 24626295, 2014). "Combination of ALOX12 inhibitors (baicalein and BMD122) and radiation therapy have synergistic inhibitory effects on the growth of LNCaP and PC-3 prostate cancer cells as well as prostate cancer xenografts in SCID mice." (PMID 38612771, 2024).
Hepatic steatosis (4 papers, 2018 to 2024). Steatosis is a term used to denote lipid accumulation within hepatocytes. "Conversely, ALOX12/15 inhibition in rodent models inhibited oxidative stress, β cell deterioration, hepatic steatosis, and systemic inflammation." (PMID 30135298, 2018). "Similarly, our findings revealed that the deletion of miR‐30a‐5p after HFD increased the expression of ALOX5 and ALOX12, which further led to hepatic steatosis through lipid peroxidation of the liver." (PMID 39360667, 2024). "Our results also showed that miR‐30a‐5p regulated gut microbiota through ALOX5, ALOX12 and COX2 – key enzymes of the arachidonic acid pathway – affecting hepatic steatosis and dyslipidaemia in mice." (PMID 39360667, 2024).
melanoma (4 papers, 2022 to 2024). A malignant, usually aggressive tumor composed of atypical, neoplastic melanocytes. "The first was in ALOX12, a biomarker of melanoma, which has an eQTL in skin that is likely mediated via an meQTL effect on a CpG island near the ALOX12 TSS." (PMID 39137780, 2024). "In a syngeneic tumor model of non-small cell lung cancer and melanoma, ALOX12 inhibition was showed to mitigate the effect of pre-radiation on the growth of pulmonary tumor nodules." (PMID 38612771, 2024).
Obesity (4 papers, 2018 to 2025). Accumulation of substantial excess body fat. "Several of the observed DMCs were located in genes related to T2D or obesity, such as ALOX12, PAMR1, and GNAS in WB; IRS1, LEP, and ADIPOQ in SAT; LCAT, FOXA2, KCNQ1, and GCKR in VAT; and PKD4, HNF4A, XBP1, and PON1 in LT." (PMID 29466957, 2018).
osteoporosis (4 papers, 2009 to 2024). A condition of reduced bone mass, with decreased cortical thickness and a decrease in the number and size of the trabeculae of cancellous bone (but normal chemical composition), resulting in increased fracture incidence. "ALOX12 enzyme, encoded by the ALOX12 gene, produces lipid peroxides, leading to oxidative stress and the development of osteoporosis." (PMID 37107290, 2023). "Our results showed that the ALOX12 gene methylation levels in the samples from patients with osteoporosis were significantly higher than those in normal controls." (PMID 37588196, 2024). "In a further subgroup analysis, the bone marrow samples from males and whole blood samples from females with osteoporosis also had significantly higher ALOX12 methylation levels than the normal controls." (PMID 37588196, 2024). "A positive correlation between ALOX12 gene polymorphism and bone mineral density (BMD) has also been verified, indicating that serum Se deficiency was accompanied by some ALOX12 variation, contributing to the peak BMD and the development of osteoporosis." (PMID 37588196, 2024). "Studies using pharmacological inhibitors or gene abrogation have indicated that the Alox12/15 pathway can be a potential therapeutic target in several disease models, such as oxidative stress-induced neuronal cell death, focal ischemia, and osteoporosis." (PMID 29772700, 2018). "Thus, we confirmed that there is hypermethylation of ALOX12 in both the rat model of osteoporosis and human patients with osteoporosis, suggesting that it may participate in the development of this disease." (PMID 37588196, 2024). "To investigate the contribution of DNA methylation in ALOX12 and CBS during osteoporosis, we performed ovariectomy to induce osteoporosis-like symptoms in rats." (PMID 37588196, 2024). "Taken together, our experiments in the rat model demonstrate that there is hypermethylation of ALOX12 and CBS, and this correlated with the presence of osteoporosis and with decreased protein expression of these targets." (PMID 37588196, 2024). "The analyzed polymorphisms belonging to a wide variety of genes, e.g., SOD, PON, GPx, GST, TXN, CAT, ALOX12, GSR, and NOS, focused on BMD variation, which is the current clinical gold standard for analyzing reductions in bone mass and diagnosing osteoporosis." (PMID 37107290, 2023). "Moreover, the protein expression of ALOX12 and CBS was also lower in the osteoporosis model group as indicated by Western blotting." (PMID 37588196, 2024).
ovarian carcinoma (4 papers, 2023 to 2025). A malignant neoplasm originating from the surface ovarian epithelium. "ALOX12 may be a possible risk factor for OC, as inhibition of ALOX12 decreases the migration and proliferation of ovarian cancer cells." (PMID 39192972, 2024). "The ferroptosis driving gene ALOX12, for instance, was found to be overexpressed in ovarian cancer cells and induce lipid production, showing high sensitivity and specificity for serous ovarian cystadenocarcinoma." (PMID 39192972, 2024). "In this study, we found that ALOX12 was differentially expressed between normal ovarian tissues and ovarian cancer tissues." (PMID 36851083, 2023). "Some scholars have constructed a prognostic grading model of ovarian cancer containing 5 ferroptosis-related factors (ALOX12, ACACA, SLC7A11, FTH1, and CD44) through biological analysis, which showed great value in the prognostic analysis of this disease." (PMID 37304234, 2023). "Heatmap and forest plot results showed that ALOX12 was overexpressed in ovarian cancer tissues with a high hazard ratio." (PMID 36851083, 2023). "ALOX12 reached its maximum weight in the five-gene signature, indicating that ALOX12 might be an important biomarker for predicting ovarian cancer prognosis." (PMID 36851083, 2023). "Similarly, we found that ALOX12 was overexpressed in ovarian cancer cells, and inhibition of ALOX12 attenuated the proliferation and migration of ovarian cancer cells." (PMID 36851083, 2023).
pancreatic cancer (4 papers, 2021 to 2024). "Compared with pancreatic cancer precursors and normal pancreatic ducts, the expression of ALOX12 in pancreatic cancers is significantly down-regulated and inhibits the proliferation of PAAD cells." (PMID 35033072, 2022). "Arachidonate 12-lipoxygenase (ALOX12) and 12-hydroxyeicosatetraenoic acid contribute to stromal aging-induced progression of pancreatic cancer." (PMID 34858977, 2021). "Similar studies have demonstrated the use of both ALOX12 and ALOX5 inhibitors in pancreatic cancer cells PANC-1 and Capan2, which were shown to express ALOX5 and ALOX12." (PMID 38612771, 2024). "In vitro and in vivo experiments respectively in MiaPaCa-2, AsPC-1 human pancreatic cancer cell lines, and athymic mice xenograft models, show that inhibitors of ALOX5 (Rev-5901) and ALOX12 (baicalein) induce growth inhibition while activating apoptosis via the mitochondrial pathway." (PMID 38612771, 2024). "To clarify the functional role of signature genes in PAAD cells, we used Cancer Cell Line Encyclopedia (CCLE) database to analyze the expression of ALOX5, ALOX12 and CISD1 in pancreatic cancer cells, and found that the expression of ALOX5 was relatively highly expressed in T3M4 cells." (PMID 35033072, 2022). "The results obtained with qPCR and IHC assays showed that ALOX5 was highly expressed regardless of whether ALOX12 and CISD1 were expressed at low levels in these pancreatic cancer tissue samples." (PMID 35033072, 2022).
cervical cancer (3 papers, 2021 to 2025). A primary or metastatic malignant neoplasm involving the cervix. "Work has shown that in cervical cancer cells, upregulation of MiR-7-5p promotes radiotherapy resistance by silencing arachidonate 12-lipoxygenase (ALOX12) and other components of ferroptosis signaling, thus limiting radiotherapy efficacy." (PMID 34830482, 2021).
heart failure (3 papers, 2018 to 2026). Inability of the heart to pump blood at an adequate rate to meet tissue metabolic requirements. "A recent study further showed that cardiac fibrosis was increased in Alox12/15 transgenic mice and was associated with the infiltration of macrophages, indicating its role in the pathogenesis of inflammation and fibrosis in heart failure." (PMID 29772700, 2018).
hepatocellular carcinoma (3 papers, 2019 to 2021). A malignant tumor that arises from hepatocytes. "ALOX12, a member of a nonheme lipoxygenase family of dioxygenases, plays a crucial role in ALOX12-12HETE-GPR31 signaling axis and was dysregulated in recurrence of hepatocellular carcinoma." (PMID 33519933, 2021).
Hyperglycemia (3 papers, 2021 to 2024). An increased concentration of glucose in the blood. "In the existence of hyperglycemia, ALOX12 also causes endothelial dysfunction and renal vasoconstriction, leading to renal injury and CKD progression." (PMID 34545296, 2021). "Because ALDOB, ALOX12, and KHK-A have been reported to promote fructose-induced cancer metastasis, we determined which of the three participated in hyperglycemia-induced cell migration." (PMID 38200154, 2024).
acute kidney injury (2 papers, 2024 to 2025). Sudden and sustained deterioration of the kidney function characterized by decreased glomerular filtration rate, increased serum creatinine or oliguria. "For instance, both protopanaxadiol and baicalein have been proven to improve cisplatin-induced acute kidney injury, but their effects are mainly limited to different ferroptosis pathways—targeting GPX4 and ALOX12, respectively." (PMID 41303615, 2025). "Selective ALOX12/15 inhibitor baicalin has been found to effectively mitigate cisplatin‐induced acute kidney injury and CPT‐11‐induced gastrointestinal dysfunction by suppressing ALOX12/15‐dependent ferroptosis." (PMID 39568772, 2024).
acute myeloid leukaemia (2 papers, 2014 to 2024). "Interestingly, in acute myeloid leukaemia the hypermethylation of ALOX12 has been associated with poorer prognosis and overall survival, while the demethylation of ALOX12 observed during chemotherapy was found to be associated with treatment response." (PMID 24626295, 2014).
alcoholic hepatitis (2 papers, 2020 to 2024). Acute hepatitis resulting from ingestion of alcohol. "Moreover, we asked if therapeutic application of LXA4, a well-characterized SPM with pro-resolving activity at least in mice, improves liver damage in Alox12/15−/− and Alox12/15+/+ mice subjected to an established animal model of alcoholic hepatitis." (PMID 32760397, 2020).
asthma (2 papers, 2021 to 2024). "In humans, a hypomethylation of ALOX12 is associated with asthma in children." (PMID 34064822, 2021).
atopic dermatitis (2 papers, 2023 to 2024). "Additionally, the excretion of its metabolite 12(S)-hydroxyeicosatetraenoic acid in urine is significantly increased in individuals with psoriasis, and most recently, an increase in Alox12 expression has been observed in mouse models of atopic dermatitis." (PMID 39137780, 2024).
bladder cancer (2 papers, 2010 to 2021). "In addition, other publicly available data from The Cancer Genome Atlas (TCGA) showed that lower expression of MLL4 was significantly associated with both lower expression of ALOX12 and higher expression of GPX4 in human head and neck SCC as well as bladder cancer." (PMID 34890228, 2021).
colorectal polyp (2 papers, 2019 to 2023). "For the ALOX12 SNPs, total colorectal polyp risk reduction by aspirin was restricted to common homozygotes, but not those with one or more minor alleles (Pint = 0.02 for rs2073438 and rs2920421, and Pint = 0.06 for rs2271316)." (PMID 37756582, 2023). "Furthermore, we detected the expressions of ALOX5, ALOX12, ALOX15 and ALOX15B in colorectal polyp." (PMID 31528237, 2019).
colorectal tumor (2 papers, 2019 to 2022). "A previous study reported upregulation of Alox12 in colorectal tumors, which is involved in inflammation." (PMID 31795377, 2019). "They showed that the expression level of ALOXE3, ALOX5, ALOX12, and ALOX12B was upregulated in colorectal tumor samples." (PMID 35928873, 2022).
coronary heart disease (2 papers, 2016 to 2022). "Lastly, coexpression network analysis was undertaken on smoking-related hub genes of coronary heart disease in GeneMANIA, and then, ITGA2B, ALOX12, ESLP, and CLU were acquired." (PMID 35096131, 2022). "The increased expression of ALOX15 mRNA in ischemic heart disease is in agreement with our earlier results but we had not previously investigated ALOX15B or ALOX12 expression in ischemic heart tissue." (PMID 27552229, 2016). "In this study, we showed that expression of ALOX15 (but not ALOX15B or ALOX12) and 15-HETE levels were substantially higher in myocardial tissue from patients undergoing heart surgery for ischemic heart disease compared with myocardial tissue from those undergoing AVR surgery." (PMID 27552229, 2016).
ischemia (2 papers, 2022 to 2025). A hypoperfusion of the BLOOD through an organ or tissue caused by a PATHOLOGIC CONSTRICTION or obstruction of its BLOOD VESSELS, or an absence of BLOOD CIRCULATION. "Our recent study also demonstrated that the ALOX12-12-HETE-GPR31 axis is critical for hepatic ischemia/reperfusion injury." (PMID 40892510, 2025).
ischemic stroke (2 papers, 2020 to 2024). A stroke disorder caused by obstruction of blood flow to the brain, due to thrombotic (local blood clot formation) or embolic (due to a blood clot or other material traveling from another site) event. "Pharmacological inhibition of ALOX12/15 in a mouse model of ischemic stroke led to neuronal protection and improved behavioural outcomes." (PMID 32438682, 2020).
myocardial ischemia (2 papers, 2022 to 2024). A disorder of cardiac function caused by insufficient blood flow to the muscle tissue of the heart. "12/15-Lipoxygenase produced by ALOX12/15 promotes oxidative stress and myocardial ischemia/reperfusion injury." (PMID 36523490, 2022).
prostate tumors (2 papers, 2014 to 2022). "All prostate tumors were found to be hypermethylated in both ALOX12 and PDGFRB, while the 2 BPH samples remained unmethylated (Spearman coefficient 0.67 and 0.78 respectively)." (PMID 24626295, 2014). "In our research, a high expression of ALOX12 revealed worse OS, RFS, and PFS in CRC, which was consistent with previous reports in kidney, breast, and prostate tumors." (PMID 35833141, 2022).
rectal cancer (2 papers, 2016 to 2022). A primary or metastatic malignant neoplasm that affects the rectum. "Carriers of a G minor allele at locus rs11571339 of the ALOX12 gene showed a lower risk for rectal cancer in those with low n-3 PUFA intake compared to higher intakes." (PMID 26891335, 2016). "ALOX12 (rs2073438) was associated with a lower risk of rectal cancer.ALOX15 (rs4796535 and rs2619112) was associated with an increased risk of rectal cancer." (PMID 35928873, 2022). "In regards to colon and rectal cancers, certain individuals may benefit largely from including LCn-3 PUFA in their diets while others do not, as demonstrated by polymorphisms in ALOX12, ALOX15 and PGES genes." (PMID 26891335, 2016).
renal carcinoma (2 papers, 2023 to 2024). A carcinoma arising from the epithelium of the renal parenchyma or the renal pelvis.
Sepsis (2 papers, 2020 to 2023). Sepsis is defined as life-threatening organ dysfunction caused by a dysregulated host response to infection. "CMTM5, SELP, and TREML1 were also observed in pediatric resolved SIRS, in addition to ALOX12 (arachidonate 12-lipoxygenase, 12S type), which was also seen in pediatric sepsis." (PMID 32318053, 2020). "The boxplot revealed 26 differentially expressed genes between the sepsis-induced ALI and control samples: Ncf2, Slc2a6, Cd44, Txnip, Slc2a1, Ubc, Hspb1, Zfp36, Arntl, Ddit4, Tnfaip3, Txnrd1, Mt1, Hmox1, Gch1, Gclc, Stat3, Egfr, Hif1a, Bach1, Socs1, Dusp1, Cdkn1a, Fth1, Steap3, and Alox12." (PMID 37081490, 2023).
Stroke (2 papers, 2014 to 2023). Sudden impairment of blood flow to a part of the brain due to occlusion or rupture of an artery to the brain. "Methylation of ALOX12 has been associated with carotid artery intimal thickness, which is a risk factor for stroke and vascular dementia." (PMID 37239136, 2023). "Importantly, in a mouse model of cerebral ischemia, ALOX12/15 inhibition protected cells against oxidative stress and the ALOX12/15 inhibitor reduced infarct sizes both 24 hours and 14 days post-stroke with improved behavioral parameters." (PMID 24533104, 2014).
tendinopathy (2 papers, 2017 to 2022). "Furthermore, immunostaining for markers of enzymes implicated in inflammation (PDPN/15PGDH/COX2) and receptors and enzymes implicated in resolution (PDPN/ERV1/ALOX12) revealed expression of these proteins in early tendinopathy." (PMID 38655164, 2022). "This increase in both SPM and eicosanoids in tendon derived stromal cells from patients with tendinopathy was coupled with a significant increase in the expression of several of their biosynthetic enzymes including ALOX12, ALOX15 and PTGS2." (PMID 28887458, 2017).
alcoholic steatohepatitis (1 paper, 2020). "Consequently, analyzing the impact of pro-resolving mediators on hepatic damage in alcoholic steatohepatitis using Alox12/15 knockout is influenced by the generation of HODEs, due to a linoleic acid-enriched diet in the NIAAA model." (PMID 32760397, 2020). "A mouse model for alcoholic steatohepatitis (NIAAA model) was tested in Alox12/15+/+ and Alox12/15−/− mice, with or without supplementation of LXA4." (PMID 32760397, 2020).
arteriosclerosis (1 paper, 2024). A vascular disorder characterized by thickening and hardening of the walls of the arteries. "The findings also revealed that changes in ALOX12 protein expression levels were positively correlated with IFTA scores and interstitial inflammation but not with glomerular lesions, arteriolar hyalinosis, and arteriosclerosis." (PMID 38345057, 2024).
autosomal recessive congenital ichthyosis (1 paper, 2022). Autosomal recessive form of inherited ichthyosis. "It has been established that ALOX12, ALOX12B, and ALOXE3 mutations can cause autosomal recessive congenital ichthyosis (ARCI)." (PMID 36684424, 2022).
B-cell lymphoma (1 paper, 2022). "Interestingly, some of these genes, such as LEP, ALOX12, RARRES2, DLEU7, and FOXR1, have been reported to be associated with other hematologic malignancies, including AML, chronic lymphocytic leukemia (CLL), and B-cell lymphoma." (PMID 35847864, 2022).
colitis (1 paper, 2024). Inflammation of the colon. "In our GEO data analysis of UC patients, “Pyroptosis”, “Regulated necrosis”, and “Apoptosis” were positively correlated with UC patients, which supports our result showing increased expression of RIPK1 and RIPK3, but not ALOX12 and GPX4, in the acute colitis model." (PMID 38491049, 2024).